HDAC6 (histone deacetylase 6)
Diseases named in the same sentence as HDAC6 in open-access papers (continued):
Sharing a sentence is not in itself a finding about the gene and the disease.
cancer (continued). "Moreover, understanding the activation state of both HDAC6’s enzymatic and nonenzymatic functions could further help in identifying the most effective strategy for targeting HDAC6 in cancer." (PMID 39941046, 2025). "HDAC6 plays a multifaceted role in regulating several cellular processes, including cell cycle progression, proliferation, migration, protein trafficking and degradation, cell shape modulation, as well as autophagy, apoptosis, and chemotherapy sensitivity in various cancers." (PMID 41300448, 2025). "Therefore, the discovery of HDAC6 and immunotherapy-target dual inhibitors may provide a novel strategy for cancer treatment by taking advantage of both immunotherapeutic and epigenetic drugs." (PMID 40572474, 2025). "Furthermore, combining HDAC6 or AURA inhibitors with inhibitors of other pathways overactive in cancer cells, such as WNT or GFR (growth factor receptor) signaling, can more effectively halt cancer progression and potentially overcome resistance to single-pathway inhibitors." (PMID 40483459, 2025). "Thus, while in NDs blocking inflammation and HDAC6-dependent inflammasome activation may be exploited as a strategy to prevent, treat, and/or ameliorate NDs symptoms, in cancer, the inhibition of this specific HDAC6 function is a double-edged sword." (PMID 39595195, 2024). "HDAC6 mediates and coordinates the major pathways involved in the degradation of misfolded and aggregated proteins, which are functions dependent on molecular chaperones that were demonstrated to play an essential role in promoting apoptosis or cell cycle arrest in human cancer cells." (PMID 37628767, 2023). "Moreover, by inhibiting the release of exosomes containing GRP78 from cancer cells, HDAC6 inhibition also inhibits angiogenesis as GRP78 is involved in blood vessel formation in growing tumors through the activation of HIF-1α and VEGF/VEGFR, as well as the PI3K/AKT, ERK, and FAK signaling pathways." (PMID 38258065, 2023). "Thus, HDAC6 can serve as a target for developing anti-cancer drugs." (PMID 36076996, 2022). "By modulating various mechanisms involved in immune recognition and tumor survival, such as down-regulating PD-L1, PD-L2 and B7-H4, the application of HDAC6 inhibitors exhibited an anti-tumor effect, which might provide theoretical basis to apply HDAC6 inhibitors in cancer immunotherapy." (PMID 35585975, 2022). "Thus, HDAC6-promoted autophagy is closely related to anti-cancer drug resistance." (PMID 36076996, 2022). "Thus, HDAC6-promoted autophagy plays a role in cancer cell proliferation." (PMID 36076996, 2022). "Given the key epigenetic involvement of HDAC6 in the autophagic process and the controversial role of autophagic machinery in promoting or blocking tumor development, designing a tailored therapy for different cancer types based on the use of specific HDAC6 inhibitors could be a valid approach." (PMID 34944907, 2021). "ACY-1215 (also known as ricolinostat) is a potent and selective HDAC6 inhibitor; we used it in the in vivo experiment based on its antitumor effects and efficacy, both alone and in combination with various conventional treatments for cancer and in several clinical trials." (PMID 34345016, 2021). "Thus, the selective targeting HDAC6 could be a potential approach to overcome drug resistance in cancer while reducing the overall toxicity seen using less selective HDAC inhibitors." (PMID 34323266, 2021). "For p62, as with HDAC6, we were unable to detect staining in healthy tissue, while we did see a very marked staining in tumor tissue, indicating that autophagy could be increased in this type of cancer." (PMID 34073238, 2021). "Given the extensive research on the special structure, substrate, and biological function of HDAC6, it could be considered as an important potential therapeutic target for numerous diseases, including cancer, neurodegenerative disease, and inflammatory diseases." (PMID 34938729, 2021).
cancer (continued). "Therefore, targeting HDAC6 could be a prospective cancer immunotherapy, as inhibition of its site showed improvement in tumorigenesis, through reducing histone hypoacetylation and increasing tumor-suppressor genes." (PMID 34684020, 2021). "Firstly, the intrinsic ability of HDAC6 to deacetylate NF-κB, having been detected to hamper the invasion of cancer, was destructed by HBx through transrepression, which might gradually create a potent microenvironment favorable to the malignant transformation of cells." (PMID 32878239, 2020). "Nevertheless, some microRNAs stimulating cancer cell proliferation and metastasis formation (miR-22, miR-221, miR-433, and miR-548), and stem cell differentiation (miR-26a), are predicted to interact with HDAC6 protein, thus inducing a destabilization or repression of the translation of its mRNA." (PMID 32013157, 2020). "Thus, downregulating HDAC6 expression may have greater anti-cancer effects compared to enzymatic inhibition with small molecule inhibitors." (PMID 33322608, 2020). "Furthermore, HDAC6 also upregulates several critical factors in the immune system, such as program death receptor-1 (PD-1) and program death receptor ligand-1 (PD-L1) receptor, which are the main targets for cancer immunotherapy." (PMID 30176876, 2018). "Our data suggest that HDAC6 inhibitor could facilitate the eradication of potentially precancerous cells at the initial stage of carcinogenesis, implying that HDAC6 inhibitor can be applied not only to cancer treatment, but also cancer prevention." (PMID 29391412, 2018). "The finding that HDAC6 deficiency or inhibition suppressed the accumulation of both wild type FGFR3 and mutant activated FGFR3 led to studies performed here that tested the effectiveness of tubacin and HDAC6 inhibition as a therapeutic strategy in FGFR3-dependent cancers." (PMID 29423038, 2018). "Importantly, HDAC6 inhibitors have been shown to be safe and active as add-on cancer therapy." (PMID 30270813, 2018). "However, it warrants further in-depth studies to explore whether cancer cells with SPOP-mutant genetic status are more sensitive to HDAC6 specific inhibitors due to elevated HDAC6 protein abundance." (PMID 28599312, 2017). "Previous studies have demonstrated that HDAC6 could induce the EMT in cancer cells." (PMID 28599312, 2017). "Both SAHA and U0126 exhibited similar effects on colony formation inhibition, and the combination of SAHA and U0126 gave the additive effect, suggesting that MAPK could also activate a HDAC6 independent pathway to promote cell growth in K-ras mutant cancer cells." (PMID 26848526, 2016). "Together with the notion that a high level of HDAC4, HDAC5 and HDAC6 expression has an implication in cancer development, the up-regulation of HDAC4, HDAC5 and HDAC6 of fPMSCs showed in this study may imply a potential risk for malignant transformation for this type of cells." (PMID 25671548, 2015). "HDAC6 may perform different functions and possess different activities in different cancers." (PMID 26388610, 2015). "Therefore, targeting HDAC6 for cancer therapy may be a good strategy due to its important role in providing an advantage to cancer cells to survive." (PMID 25774669, 2015). "Although deacetylation of α-tubulin by HDAC6 and subsequent Smad3 activation seems to be an important event in the induction of invadopodia production in hypoxia, other data link HDAC6 to tumor progression and cancer cell invasion through deacetylation of other cytoplasmic substrates." (PMID 23405166, 2013). "However, why LBH589 selectively down-regulating HDAC6 proteins and Aurora kinases A and B in certain specific cancer cell lines remains unclear." (PMID 24023871, 2013). "Conversely, after Hdac6 is restored to the nucleus upon cellular transformation, it may re-direct Tip60-p400 to a subset of its target genes that are normally stem cell-specific, potentially eliciting changes in gene expression that promote cancer development." (PMID 24302573, 2013).
cancer (continued). "Finally, we asked whether re-localization of Hdac6 to the nucleus in cancer cells is an early event during transformation, at a time when it might be more likely to contribute to cancer progression." (PMID 24302573, 2013). "We evaluated the HDAC-6 isoform-specific inhibitor Tubacin alongside SAHA and Trichostatin A, to compare the relative potency of anti-cancer effects of specific inhibitors with pan-inhibitors." (PMID 41395596, 2025). "Vorinostat effectively inhibits HDAC6 expression, induces cancer cell apoptosis, and reduces EAOC tumor size by blocking the ARID1A6488delG/HDAC6/IL-10 pathway." (PMID 40330466, 2025). "Some studies have shown that the signaling pathways of ROCK and histone deacetylase 6 (HDAC6) intersect during tumor progression, especially considering the cancer cell motility." (PMID 39458584, 2024). "HDAC6 is involved in PD-L1 expression through the STAT3 pathway, and its inhibition results in a reduction in PD-L1 expression in various types of cancer." (PMID 39063958, 2024). "Inappropriate expression of histone deacetylase (HDAC-6) and deregulation of the phosphatidylinositol 3-kinase (PI3K) signalling pathway are common aberrations observed in cancers." (PMID 38543175, 2024). "The HDAC6 inhibitors increased proteasome activity and pan-MHC-I expression in most cancer cell lines." (PMID 38747592, 2024). "In malignant tumors, HDAC1, 2, 4 and HDAC6 expression was observed in 14%, 82%, 36% and 18%, respectively." (PMID 37373187, 2023). "In the present study virtual screening of FDA approved drugs retrieved from the DrugBank database was carried out against the HDAC6 and VISTA cancer drug targets." (PMID 37660065, 2023). "Accordingly, treatment of cancer cells with JBI-097 resulted in a stronger and complete inhibition of cell proliferation as compared to LSD1 or HDAC6 specific inhibitors, clearly demonstrating the advantage of dual inhibition." (PMID 36595522, 2023). "Accordingly, treatment of cancer cells with JBI-097 resulted in a strong and dose-dependent increase in acetylation of alpha-tubulin, a selective cellular substrate for HDAC6." (PMID 36595522, 2023). "HDAC6 is distinct for having two catalytic domains, CD1 and CD2, making it a valuable target for treating cancer and Alzheimer's disease." (PMID 37660065, 2023). "As a dose-dependent anti-cancer effect of ACY-1215 was observed in the clonogenic assays and zebrafish xenografts, correlations between expression level of HDAC6 transcript expression and UM patient overall survival/progression-free survival were analyzed." (PMID 35159049, 2022). "We observed strong anti-cancer effects elicited by ACY-1215 treatment in a dose-dependent manner in both UM- and MUM-derived cell lines, albeit weak HDAC6 expression is reported in UM tissues." (PMID 35159049, 2022). "The resulting dual inhibitors were identified to be potent against multiple cancer lines with excellent selectivity against PI3K γ, δ isoforms, and HDAC6 enzymes." (PMID 35408693, 2022). "Thus, HDAC6 might play a role in anti-cancer drug resistance." (PMID 36076996, 2022). "Thus, HDAC6 inhibitors may enhance the sensitivity of cancer cells to the PD-L1 blockade." (PMID 36076996, 2022). "HDAC6 inhibitor C1A, in combination with phosphatidylinositol 3′-kinase (PI3K) inhibitor, also had synergistic effects on caspase 3/7 activity in various cancer cells." (PMID 36076996, 2022). "Recently, it has been shown that HDAC6 and SIRT2 act as deacetylases that regulate the acetylation status of KRAS in cancer cells." (PMID 34485153, 2021). "Inactivated by the HDAC6 inhibitor, PTEN can inhibit the signalling pathways of Notch and PI3K‐AKT‐Mtor in cancer cells to suppress BM1 activity." (PMID 33749070, 2021). "Since HDAC6 was necessary for the metastatic potential enhanced by PSA, we examined the effect of IL-27 on the metastatic potential of cancer cells." (PMID 34234781, 2021).
cancer (continued). "In our study, HDAC6 expression levels were shown to correlate with TMB and MSI in four cancer types, respectively." (PMID 34485153, 2021). "In this study, we analyzed HDAC6 expression, prognosis, TMB, and MSI in 33 tumors by pan-cancer analysis." (PMID 34485153, 2021). "Our data demonstrated that the intracellular concentration of citarinostat and the HDAC6 inhibiting activity were significantly reduced by ABCB1 and ABCG2, and consequently, cancer cells overexpressing ABCB1 or ABCG2 are insensitive to citarinostat." (PMID 33807514, 2021). "HDAC6 has been found to promote cell proliferation and migration by enhancing HSP90 chaperone function in a variety of cancer cells." (PMID 33456556, 2021). "In the present study, we used multiple datasets, such as Cancer Cell Lineage Encyclopedia (CCLE) and The Cancer Genome Atlas (TCGA) for pan-cancer analysis to reveal the precise mechanism of HDAC6." (PMID 34485153, 2021). "Recently, we identified that HDAC6 specifically regulates histone acetylation at a specific residue, H4K12, in several types of cancer, including EWS." (PMID 34345016, 2021). "A series of thieno[2,3-d]pyrimidine-based hydroxamic acid hybrids was designed and synthesised as multitarget anti-cancer agents, through incorporating the pharmacophore of EGFR, VEGFR2 into the inhibitory functionality of HDAC6." (PMID 34187263, 2021). "Accordingly, LBH589 (Panobinostat), an inhibitor of histone deacetylase 6 (HDAC6), was used to inhibit the HSP90 activity in cells of several carcinoma cell lines that became radiosensitized in such a way." (PMID 33806538, 2021). "Because α‐tubulin has been newly validated as a substrate for HDAC8 except for HDAC6, the expression and deacetylating tubulin level of HDAC6 differed from HDAC8 in kinds of cancer cells." (PMID 32885602, 2020). "Several reports revealed that HDAC6, a member of the HDAC IIb subfamily, regulates the progression of diverse diseases including cancer, bone remodeling, and vascular remodeling." (PMID 32375326, 2020). "To further explore the cooperation of RUNX2 and HDAC6 in inducing transcription of cancer related genes, we investigated their binding on the promoters of a selected set of genes identified as commonly repressed upon RUNX2 and HDAC6 silencing." (PMID 31395086, 2019). "Several modified analogues exhibited high dual HDAC6/8 selectivity which can be used as a kind of chemical tool to clarify the function of HDAC6 and HDAC8 in cancer biology." (PMID 30886064, 2019). "As a migration and invasion inhibitory protein and a metastasis suppressor, MIIP was reported to bind to and antagonize the function of diverse effectors, including IGFBP-2, HDAC6 and PAK1, depending on different molecular context in different cancer types." (PMID 31092266, 2019). "Immunohistochemical expression of HDAC6, hypoxia inducible factors-1α (HIF-1α), programmed death-1 ligand (PD-L1), CD44 (cancer stem cell marker), and ARID1A was analysed for 106 OCCC patients." (PMID 30787326, 2019). "In particular, through inhibition of HDAC6, HDAC inhibitors reduce microtubule acetylation preventing the migration of cancer cells." (PMID 30096875, 2018). "By contrast, histone deacetylase 6 (HDAC6) was inversely correlated with miR-22 in both cervical tissues and cancer cell lines." (PMID 30379969, 2018). "Cytosolic deacetylase histone deacetylase 6 (HDAC6) is involved in the autophagy degradation pathway of malformed proteins, an important survival mechanism in cancer cells." (PMID 30318510, 2018). "Together, our data identify the tumor suppressor SPOP as an upstream negative regulator for HDAC6 stability, and SPOP loss-of-function mutations might lead to elevated levels of the HDAC6 oncoprotein to facilitate tumorigenesis and metastasis in various human cancers." (PMID 28599312, 2017).
cancer (continued). "For example, overexpression of HDAC1, HDAC2, HDAC4, HDAC6, and HDAC7 has been observed in various cancers." (PMID 27902771, 2016). "Thus, HDAC6 might provide a new target for cancer treatment." (PMID 25946558, 2015). "We find that para-substituted hydroxamic acid analogs of 9b inhibit HDAC activity showing preference for HDAC6 over HDAC1 and have cancer selective antiproliferative properties." (PMID 26698121, 2015). "Inhibition of HSP27 has been reported to induce the degradation of the histone deactylase HDAC6, transcription factor STAT2 and procapase-3 in human cancer cells." (PMID 23555679, 2013). "Thus, HDAC6 may serve as a pivotal therapeutic target for HDACIs in cancer treatment." (PMID 24023871, 2013). "Since LBH589 is a potent hydroxamate group HDACI with strong inhibitory effect on HDAC6, LBH589 has the advantage of clinical application in the treatment of cancers with HDAC6 expression." (PMID 24023871, 2013). "LBH589 induces sustained ERK activation through a free forward regulation between HDAC6 and ERK in cancer cells, which not only induces prometaphase arrest but also triggers apoptosis." (PMID 24023871, 2013). "Although the regulation of HDAC6 by phosphorylation has not been extensively studied in the cancer context, many of the kinases which interact with HDAC6 are key mediators of oncogenic signalling." (PMID 39941046, 2025). "Although combination therapies involving HDAC6 inhibitors have demonstrated better efficacy across various cancer types, these therapies are not without challenges, including producing overlapping toxicities." (PMID 39941046, 2025). "While inhibition of HDAC6 may prevent cell migration, inhibition of HDAC11 has been shown to increase the migratory activity of cancer cells." (PMID 40943415, 2025). "We also analyzed the correlation between CSNK2B expression and HDAC family‐related genes in the TIMER2.0 public database of multi‐cancer, and we found that the expression of CSNK2B showed a positive correlation with HDAC1, HADC2, HDAC5, HDAC6, and HDAC8 in LUAD and LUSC." (PMID 40013761, 2025). "The atypical protein kinase C zeta (PKC ζ), which can act as either a tumour suppressor or promoter, depending on the cancer type, forms a complex with HDAC6 and was shown to phosphorylate serine and threonine residues in both the CD1 and CD2 catalytic domains of HDAC6." (PMID 39941046, 2025). "Given HDAC6′s widespread expression in both malignant and non-malignant brain tissues—and the growing interest in HDAC6 as a therapeutic target in cancer —we investigated the effects of its selective inhibition using tubastatin." (PMID 40843669, 2025). "Given its unique structure and functions, HDAC6 is being considered a promising cancer therapeutic target, with four HDAC inhibitors—vorinostat, romidepsin, belinostat, and panobinostat—approved for various cancers." (PMID 39594707, 2024). "Treatment of either CD8+ T cells or cancer cells with the HDAC6 inhibitors alone did not significantly increase the generation of annexin-V+/propidium iodide+ cells." (PMID 38747592, 2024). "The development of dual‐target HDAC6 inhibitors for cancer therapy is an area of active research, with promising candidates such as dual HDAC6/PI3K inhibitors, dual HDAC6/mTOR inhibitors, dual HDAC6/BRD4 inhibitors, and dual HDAC6/HSP90 inhibitors in various stages of development." (PMID 39492834, 2024). "Furthermore, the histone deacetylase HDAC6 and the zinc finger E-box-binding homeobox 1 (ZEB1) proteins were shown as differentially expressed in several cancers and are involved in tumor immune infiltration and TME." (PMID 36672310, 2023).